PTGER3 (prostaglandin E receptor 3)
Description:
Receptor for prostaglandin E2 (PGE2). The activity of this receptor can couple to both the inhibition of adenylate cyclase mediated by G(i) proteins, and to an elevation of intracellular calcium. Required for normal development of fever in response to pyrinogens, including IL1B, prostaglandin E2 and bacterial lipopolysaccharide (LPS). Required for normal potentiation of platelet aggregation by prostaglandin E2, and thus plays a role in the regulation of blood coagulation. Required for increased HCO3(-) secretion in the duodenum in response to mucosal acidification, and thereby contributes to the protection of the mucosa against acid-induced ulceration. Not required for normal kidney function, normal urine volume and osmolality (By similarity).
Synonyms: EP3; lnc003875; EP3-I; EP3-II; EP3-III; EP3-IV; EP3-VI; EP3e; PGE2-R
Tractability: Small molecule: an approved drug acts on it; a structure with a bound ligand is known; a high-quality ligand is known; it belongs to a druggable protein family. Antibody: UniProt places it where antibodies can reach, with high confidence; its Gene Ontology location is reachable by antibodies, with high confidence; UniProt predicts a signal peptide or a membrane-spanning region. PROTAC: a small molecule that binds it is known.
Target class: Lipid-like ligand receptor (family A GPCR); Membrane receptor; Prostanoid receptor; Small molecule receptor (family A GPCR); Family A G protein-coupled receptor
Chemical probes: CHEMBL217941, CHEMBL220802, PD081781, PD081827, PD082510, PD083304, PD083540, PD083554, PD083688, PD083899, PD084252, PD084539, PD084700, PD084760, PD084939
Safety:
Unwanted effects reported when the protein is acted on. In parentheses: how it was acted on, where the effect was seen, and who reports it.
aspirin-intolerant asthma (source: ClinPGx)
cough (source: ClinPGx)
not been studied (source: ClinPGx)
Gene: Protein-coding gene on chromosome 1 (70,852,353 to 71,047,816, reverse strand). Ensembl gene ENSG00000050628.
Subcellular location: Cell membrane
Pathways (Reactome):
Signal Transduction: G alpha (i) signalling events; Prostanoid ligand receptors
Gene Ontology:
Molecular function: prostaglandin E receptor activity; G protein-coupled receptor activity; prostaglandin receptor activity
Biological process: adenylate cyclase-activating G protein-coupled receptor signaling pathway; cell death; G protein-coupled receptor signaling pathway; inflammatory response; intestine smooth muscle contraction; negative regulation of gastric acid secretion; phospholipase C-activating G protein-coupled receptor signaling pathway; positive regulation of cytosolic calcium ion concentration; positive regulation of fever generation
Cellular component: plasma membrane; membrane; nuclear envelope
Genetic constraint (gnomAD): Loss-of-function variants: 14 observed, 28.15 expected, observed/expected ratio (o/e) 0.5, 90% interval 0.33 to 0.78. The upper end of that interval is the gene's LOEUF score, 0.78, which puts it in group 3 of 6, group 1 being the genes least tolerant of losing a copy. Missense variants: 421 observed, 496.13 expected, observed/expected ratio (o/e) 0.85, 90% interval 0.78 to 0.92. Synonymous variants: 224 observed, 222.26 expected, observed/expected ratio (o/e) 1.01, 90% interval 0.9 to 1.13.
Homologues: Orthologues: chimpanzee PTGER3 (94% identical), macaque PTGER3 (92% identical), rabbit PTGER3 (87% identical), pig PTGER3 (83% identical), mouse Ptger3 (79% identical), dog PTGER3 (79% identical), rat Ptger3 (79% identical), guinea pig PTGER3 (74% identical), tropical clawed frog ptger3 (58% identical), zebrafish ptger3 (55% identical), Drosophila melanogaster CG7497 (23% identical). Paralogues in human: PTGFR (29% identical), PTGER1 (29% identical), TBXA2R (27% identical), PTGIR (25% identical), PTGER4 (24% identical), PTGDR (23% identical), PTGER2 (23% identical).
Diseases named in the same sentence as PTGER3 in open-access papers:
PTGER3 is named in the same sentence as 142 diseases in open-access papers, as found by Europe PMC text mining. Sharing a sentence is not in itself a finding about the gene and the disease. The quoted sentences say what the papers report.
breast cancer (14 papers, 2011 to 2026). A primary or metastatic malignant neoplasm involving the breast. "Further validation is needed to show the relation between PTGER3 and estrogen receptor status in breast cancer." (PMID 23284898, 2012). "Previous studies have found that the PTGER3 gene is upregulated in various breast cancer subtypes." (PMID 36467500, 2022). "Furthermore, the integration of network pharmacology and molecular docking analyses revealed key targets associated with the anti-tumor effects of the pericarp, including PTGER3, DRD2, and ADORA2A, which present novel therapeutic targets for breast cancer treatment." (PMID 39682950, 2024).
colon cancer (12 papers, 2008 to 2025). "PTGER3 encodes a receptor for prostaglandin E2 that is targeted by misoprostol, an approved drug for gastric ulcers and reflux disease and which has shown efficacy in colon cancer xenograft models." (PMID 40447568, 2025). "For example, high CHRM3 levels are linked to invasion and metastasis in colon cancers; loss of EPN1 was linked to elevated VEGFR2 degradation and disorganized angiogenesis; and elevated PTGER3 levels was linked to shorter survival times in cervical cancers." (PMID 35991579, 2022). "Intriguingly, deletion of EP1 (Ptger1), EP3 (Ptger3), or some other PG receptor subtypes failed to suppress colon tumor formation but rather exacerbated it, suggesting the presence of PG receptor subtype oppositely functioning to colon tumor formation." (PMID 29259703, 2017).
cervical cancer (11 papers, 2017 to 2023). A primary or metastatic malignant neoplasm involving the cervix. "Interestingly, PTGER3 expression is associated as a prognostic marker for cervical cancer." (PMID 36010605, 2022). "PTGER3 promotes the tumor cell migration by regulating uPAR expression to affect cervical cancer progression." (PMID 36812479, 2023). "PTGER3 signaling promotes the migration of cervical cancer cells through the modulation of the urokinase-type plasminogen activator receptor." (PMID 36010605, 2022). "These target genes were crossed with mRNAs that are downregulated by more than fivefold in cervical cancer from The Cancer Genome Atlas (TCGA) database, and 8 target genes were finally obtained (OGN, SCN7A, PGR, PTGER3, FGF7, ADAMTS5, LMO3 and ANK2)." (PMID 35513835, 2022). "Meanwhile, according to MCC scores from the CytoHubba plugin in Cytoscape, the top 5 cervical cancer-related genes were screened out (MEF2C, CXCL16, IRF4, OAS3, PTGER3)." (PMID 34020619, 2021). "PTGER2 expression is a prognostic factor for the overall survival in the subgroup of negative PTGER3, and high galectin-3 expressed cervical cancer patients." (PMID 36010605, 2022). "PTGER2 expression increases while PTGER3 expression decreases during cervical neoplasia development, suggesting these receptors might be considered as positive and negative prognostic markers of cervical cancer lesions, respectively." (PMID 36010605, 2022).
diabetes (10 papers, 2016 to 2024). "Novel drugs aiming to increase MMP-2 or decrease PTGER3 in the kidney might of great values for preventing DN and renal damages in diabetes." (PMID 33435900, 2021). "PTGER3 is the gene for prostaglandin E receptor 3 (EP3), which is reported to be upregulated in diabetes patients." (PMID 37762604, 2023). "An in vivo animal experiment showed that the knockout of PTGER3 did not reduce the levels of plasma and urine glucose in the streptozotocin-induced mouse model of diabetes." (PMID 33435900, 2021). "Interestingly, diabetes resulted in a significant reduction of Ptger1 and Ptger3 mRNA levels in macrophages; effects that were not mediated by myeloid cell EP4." (PMID 27351842, 2016).
Obesity (9 papers, 2017 to 2025). Accumulation of substantial excess body fat. "A previous study reported an obesity-induced increase in PTGER3 expression in macrophages extracted from subcutaneous adipose tissue without the dissection of tissue components." (PMID 39409051, 2024). "This led to the suggestion that PTGER3+ macrophages may play a different role in the obesity-induced expansion of subcutaneous adipose tissue than in IMAT." (PMID 39409051, 2024). "In our study, increasing BMI, a measure of obesity, was significantly associated with the accumulation of PTGER3+ macrophages in the SMFs but not IMATs of the participants." (PMID 39409051, 2024).
Hypertension (8 papers, 2009 to 2023). The presence of chronic increased pressure in the systemic arterial system. "A haplotype spanning PTGER3 (rs2206344, rs3765894, SNP_A-4228934, rs2744918, rs2268062) was associated with hypertension and it is the most common haplotype (ATAAA) that increases the risk of hypertension." (PMID 36835616, 2023). "We identified haplotypes of LEPR, but also PTGER3 gene, which were associated with increased risk for hypertension in KORA S3 study population." (PMID 19562039, 2009). "Our findings showed that nine tag-SNPs, each representing a haplotype block in the PTGER3 gene locus, and rs2268062, also in PTGER3, which was included in the study for being reportedly linked to hypertension, were significantly associated with the risk of nephrosclerosis." (PMID 34442416, 2021). "A haplotype analysis of PTGER3 recently suggested this gene may represent a risk factor for hypertension." (PMID 23155414, 2012). "In total, 12 markers in 7 genes (ADRA2A, LEP, LEPR, PTGER3, SLC2A1, SLC4A2, SLC8A1) revealed considerable association (P<10−3) either with SBP, DBP, and/or hypertension (HYP)." (PMID 19562039, 2009). "Interestingly, the most common PTGER3 haplotype ATAAA (rs2206344, rs3765894, SNP_A-4228934, rs2744918, rs2268062) was associated with the risk for hypertension (P = 1.6×10−5, OR = 1.50; hypertensives 57%; normotensives 46%), whereas two other prevalent variants exhibit a protective effect." (PMID 19562039, 2009).
endometriosis (5 papers, 2015 to 2022). The growth of functional endometrial tissue in anatomic sites outside the uterine body. "In order to further validate the expression of AGTR1 in EC and EU and to evaluate the diagnostic value of CXCL12, PTGER3, and AGTR1 in endometriosis, we need to increase the sample size." (PMID 36524127, 2022). "This suggests a role for PTGER3 in the pathogenesis of endometriosis, and why hormone therapy cannot truly cure the disease." (PMID 36524127, 2022). "In a comparative laboratory study, PTGER3 and PTGS (prostaglandin endooxidase synthase) were significantly increased in the endometrium of patients with endometriosis compared with those of normal women, and those treated with progesterone had higher levels of PTGS." (PMID 36524127, 2022).
lung adenocarcinoma (5 papers, 2020 to 2023). A carcinoma that arises from the lung and is characterized by the presence of malignant glandular epithelial cells. "PTGER3 induces tumor progression in different cancer types including adenocarcinoma of the lung." (PMID 34876106, 2021).
asthma (4 papers, 2018 to 2025). "Finally, in the asthma vs. HC comparison, 9 SNPs were identified, with 2 associated with risk in the MS4A2 gene (rs573790 p = 0.001, OR = 1.70, CI 95% = 1.21-2.37), and 7 SNPs associated with protection in 4 genes (TBXAS1, FANCC, CYSLTR2, and PTGER3)." (PMID 30254660, 2018). "In the last comparison asthma vs. control group we detected seven SNPs in four genes (TBXAS1, FANCC, CYSLTR2, and PTGER3)." (PMID 31936183, 2020).
gastric cancer (4 papers, 2021 to 2023). A primary or metastatic malignant neoplasm involving the stomach. "After meta-analysis of GC gene expression profile chip, it was found that 7 of these genes, including AKR1B1, CTSK, MMP2, TLR4, ADRB2, PDE1C, and PTGER3, had significant differences in gastric cancer tissues." (PMID 34646828, 2021). "Whole-genome analysis showed that PTGER3 is abnormally low in gastric cancer." (PMID 34646828, 2021). "Among most downregulated genes we found GPX3, PTGER3 and LIPF (−47.5 and −435.63 of fold change for Diffuse and Intestinal tumors respectively), that resulted hypermethylated in gastric cancer." (PMID 34012923, 2021). "The lack of PTGER3 leads to abnormal secretion of gastrin and gastric acid and accelerates the occurrence of gastric cancer." (PMID 34646828, 2021). "In addition, PTGER3 can also up-regulate the expression of related MMP2 and AR to promote the proliferation of cancer cells and the deterioration of gastric cancer." (PMID 34646828, 2021).
hepatocellular carcinoma (4 papers, 2020 to 2022). A malignant tumor that arises from hepatocytes. "Prostaglandin E receptor 3 was identified as a regulator involved in the response of hepatocellular carcinoma to acRoots." (PMID 35152841, 2022).
ischemia (4 papers, 2013 to 2021). A hypoperfusion of the BLOOD through an organ or tissue caused by a PATHOLOGIC CONSTRICTION or obstruction of its BLOOD VESSELS, or an absence of BLOOD CIRCULATION. "Activation of PTGER3 was shown to protect cardiomyocytes from oxidative stress and reduce ischemia-induced arrhythmias and infarct size." (PMID 24289243, 2013).
prostate carcinoma (4 papers, 2017 to 2020). A carcinoma that arises from epithelial cells of the prostate gland. "In addition, PTGER3 was found to regulate prostate cancer cell growth by targeting androgen receptors." (PMID 32236620, 2020).
endometrial cancer (3 papers, 2018 to 2020). Primary or metastatic malignant neoplasm involving the endometrium (mucous membrane that lines the endometrial cavity). "There was an increase in EP3 (PTGER3) and EP4 (PTGER4) receptor gene expression in type I and type II endometrial cancers which could lead to an increase in local PGE2-EP3/EP4 mediated signaling." (PMID 32982722, 2020).
melanoma (3 papers, 2018 to 2024). A malignant, usually aggressive tumor composed of atypical, neoplastic melanocytes. "muTARGET web-based tool allowed us to predict genes, which expression patterns can be associated with genetic polymorphism in group #1 (TBXAS1, PTGIS, and AKR1C3) or group #2 (PTGDR, PTGFR, and PTGER3) in melanoma." (PMID 35453789, 2022). "Mutation frequency of TBXAS1, PTGIS, AKR1C3, PTGDR, PTGFR and PTGER3 genes in melanoma were 5–6%, 5–7%, 2.8–5%, 3–4%, 7–9%, 2.1–5%, respectively." (PMID 35453789, 2022).
ovarian carcinoma (3 papers, 2020 to 2025). A malignant neoplasm originating from the surface ovarian epithelium. "We found that the expression intensity and quantity of PI3, RGS1, PTGER3 and CCDC80 in ovarian cancer tissue was higher than that in normal ovarian tissue." (PMID 33271935, 2020).
Alzheimer disease (2 papers, 2020 to 2022). A progressive, neurodegenerative disease characterized by loss of function and death of nerve cells in several areas of the brain leading to loss of cognitive function such as memory and language. "Additionally, PTGER3 signaling was shown to have inflammatory, amyloidogenic, and synaptotoxic effects in a mouse model of Alzheimer disease." (PMID 31929116, 2020).
bladder cancer (2 papers, 2023 to 2024). "In contrast, the 5hmC DMR of PTGER3 was hypermethylated, whereas its expression was also markedly upregulated in recurrent bladder cancers." (PMID 37138354, 2023).
Nephropathy (2 papers, 2019 to 2021). A nonspecific term referring to disease or damage of the kidneys. "However, the association of PTGER3 expression with nephropathy or other renal diseases is rarely reported." (PMID 33435900, 2021). "Two or more methylated CpG sites were found in the PTGER3 gene in diabetic patients with the end-stage renal disease compared with those without nephropathy." (PMID 33435900, 2021). "What’s more, there was a differentially methylated level in the PTGER3 gene between diabetic patients with end-stage renal disease and those without nephropathy." (PMID 33435900, 2021). "Since the downregulation of PTGER3 and upregulation of MMP-2 are protective for renal diseases, the agonists of PTGER3 (including iloprost and treprostinil) and inhibitor of MMP-2 (like captopril) might be inapplicable for the treatment of DN." (PMID 33435900, 2021). "Apart from the PTGER3 gene, matrix metalloproteinase-2 (MMP-2) is also differentially methylated in diabetic patients with the end-stage renal disease compared with those without nephropathy." (PMID 33435900, 2021).
nephrosclerosis (2 papers, 2021 to 2023). Hardening of the kidney due to infiltration by fibrous connective tissue (fibrosis), usually caused by renovascular diseases or chronic hypertension. "The study of the nephrosclerosis cohort identified several variants in the PTGER3 gene associated with significant changes in renal parameters and blood pressure traits." (PMID 34442416, 2021). "In the nephrosclerosis patients, a proximal region of PTGER3 was tagged as relevant for eGFR (p values for identified SNPs ranged from 0.0003 to 0.038)." (PMID 34442416, 2021).
schizophrenia (2 papers, 2017 to 2019). A major psychotic disorder characterized by abnormalities in the perception or expression of reality. "In the context of pathology, PTGER3 has been found to be upregulated in aged patients with schizophrenia, suggesting the participation of the eicosanoid signaling in mental disorders." (PMID 28279172, 2017).
Apnea (1 paper, 2012). Lack of breathing with no movement of the respiratory muscles and no exchange of air in the lungs. "Consistency of effects between rs7030789 and rs1409986 in LPAR1 and PTGER3 and apnea phenotypes were observed in independent clinic-based cohorts." (PMID 23155414, 2012).
breast tumor (1 paper, 2022). "This can be traced in contrasting pairs such as miR-19a/PTGER2 (pancreatic tumor); miR-421/PTGER2 (uterine tumor); miR-590/PTGFR (uterine and breast tumor); miR-20a/PTGER3 (uterine tumor)." (PMID 35453789, 2022).
colorectal tumors (1 paper, 2015). "Regarding colorectal tumors PTGS2, PTGES and PTGER3 were found up-regulated in many datasets." (PMID 26498686, 2015).
Cryptosporidium infection (1 paper, 2022). "STAg-treated mice also had a lower abundance of Ccl4, the prostaglandin receptor Ptger3, and granzymes B and K, which have all previously been implicated in Cryptosporidium infection." (PMID 34928716, 2022).
endometrial adenocarcinomas (1 paper, 2011). "We found elevated expression of PTGES2 and PTGER4 and suppression of PTGER1 and PTGER3 in endometrial adenocarcinomas compared with normal endometrium." (PMID 21589857, 2011). "However, more interestingly, within this sample set we found a significant reduction in the expression patterns of PTGER1 and PTGER3 in endometrial adenocarcinomas compared with normal endometrium." (PMID 21589857, 2011). "Here, we show suppression of PTGER1 and PTGER3 and elevated expression of PTGES2 and PTGER4 in endometrial adenocarcinomas compared with normal endometrium." (PMID 21589857, 2011).
gastric tumors (1 paper, 2018). "Among these genes, we further selected six GI hormone receptors whose expression was significantly down-regulated by 80–100% in the primary gastric tumors, including neuropeptide Y receptors (NPY1R and PPYR1), prostanoid receptors (PTGDR, PTGER2, and PTGER3), and a somatostatin receptor (SSTR2)." (PMID 30510283, 2018). "The qRT-PCR and bisulfite sequencing analyses of the six genes (NPY1R, PPYR1, PTGDR, PTGER2, PTGER3, and SSTR2) demonstrated a negative correlation between methylation and gene expression in two sets of paired gastric tumor and normal tissues." (PMID 30510283, 2018).
influenza (1 paper, 2023). An acute viral infection of the respiratory tract, occurring in isolated cases, in epidemics, or in pandemics; it is caused by serologically different strains of viruses (influenzaviruses) designated A, B, and C, has a 3-day incubation period, and usually lasts for 3 to 10 days. "NJP ganglion-targeted Ptger3 knockout caused a marked attenuation of influenza-induced sickness behaviour." (PMID 36890237, 2023).